H19 (H19 imprinted maternally expressed transcript)
Diseases named in the same sentence as H19 in open-access papers (continued):
Sharing a sentence is not in itself a finding about the gene and the disease.
liver fibrosis (continued). "Further studies are necessary to dissect out cell type specific roles of Bcl2 and H19 in liver fibrosis and other chronic liver diseases." (PMID 26838806, 2016). "Additionally, an association between lncRNA H19 and LSM, an indicator of liver fibrosis, was identified." (PMID 40101079, 2025). "Additionally, hypoxia inducible factor-1ɑ (HIF-1α) induces H19 expression, activating the AMPK pathway to promote degradation of lipid droplets in HSCs, ultimately causing their activation and worsening liver fibrosis." (PMID 39195573, 2024). "Furthermore, H19 was found to be up-regulated in fibroblasts in idiopathic pulmonary fibrosis, and the H19-Sox9 axis was found to contribute to hepatocyte death and liver fibrosis, both of which were observed in HALI." (PMID 39346085, 2024). "In addition, the expression level of hepatic H19 and serum exosomal H19 is positively correlated with the severity of liver fibrosis." (PMID 35432349, 2022). "In a liver fibrosis model, a link between TGFβ and the lncRNA H19 has recently been found." (PMID 33923324, 2021). "Here, we reported that the hepatic H19 level was closely correlated with macrophage activation and hepatic fibrosis in both Mdr2-/- and bile duct ligation (BDL) cholestatic mouse models, as well as in human primary sclerosing cholangitis (PSC) and primary biliary cholangitis (PBC) patients." (PMID 31940841, 2020). "In the regulation of liver fibrosis, H19 has a relatively complex mechanism of action." (PMID 32098245, 2020). "H19 RNA is related to the development of inflammatory diseases such as ulcerative colitis and osteoarthritis, as well as organ fibrosis including liver fibrosis, renal fibrosis, and pulmonary fibrosis." (PMID 29062612, 2017). "We further confirmed the elevation of BCL2 protein levels in nonalcoholic steatohepatitis (NASH), alcohol and HCV cirrhosis by Western blot.These results demonstrated a positive correlation of activation of BCL2 and H19 with the development of liver fibrosis and cirrhosis in both humans and mice." (PMID 26838806, 2016). "When the liver injury occurs, Sox9 may act on hepatocyte extracellular matrix genes, leading to extracellular matrix deposition 78, 79 and induction of non-coding RNA H19 by binding to the conserved promoter region of the H19 gene, while participating in hepatocyte apoptosis and liver fibrosis." (PMID 38993564, 2024). "Furthermore, H19 deficiency protected mice from WDSW-induced NAFLD; and downregulation of H19 in HuRhKO mice significantly reduced WDSW-induced hepatic lipid accumulation, inflammation and liver fibrosis." (PMID 36224648, 2022). "Similarly, both exosomal and hepatic H19 levels are positively correlated with hepatic fibrosis in biliary atresia (BA) patients, and cholangiocyte‐derived exosomes delivered H19 to hepatocytes directly or via circulation and eventually promoted cholestatic liver injury." (PMID 32578911, 2020). "Therefore, the DNMT1-lncRNA H19 epigenetic pathway plays important roles in liver fibrosis." (PMID 32098245, 2020). "H19 expression is low in adult human liver but is highly induced in livers with cholestatic fibrosis and cirrhosis, indicating that H19 may be involved in the pathogenesis of liver fibrosis." (PMID 30148159, 2017). "H19 promotes the transdifferentiation of HSCs into myofibroblasts via the TGF-β1 pathway, while the downregulation of the antifibrotic miR-148a in liver fibrosis inhibits HSCs activation by targeting ubiquitin-specific protease 4 (USP4)." (PMID 39195573, 2024). "In BDL-H19KO and DKO (Mdr2−/−H19maternal Δ Exon1/+) mice, transplantation of cholangiocyte-derived exosomal H19 was preferentially and rapidly taken up by HSC-derived fibroblasts and HSCs, thus promoting hepatic fibrosis." (PMID 37326156, 2023).
liver fibrosis (continued). "Previous studies demonstrated that H19 was highly elevated in the liver of NASH, cholestatic, and CCL4‐induced liver fibrosis." (PMID 37398637, 2023). "At present, several lncRNAs have been proved to be involved in the occurrence and development of liver fibrosis by controlling PI3K/Akt signaling pathway, such as lincrna-p21, HOTAIR, and H19." (PMID 34597331, 2021). "Previous and our recent studies also showed that TCA induced the hepatic expression of H19 and fibrotic markers, triggered HSC activation and promoted systemic inflammation and liver fibrosis." (PMID 34736501, 2021). "We recently reported that the aberrant expression of long noncoding RNA (lncRNA) H19 was responsible for HSC activation and liver fibrosis progression in multiple mouse models." (PMID 34566665, 2021). "Downregulation of H19 was found in TGF-β1-stimulated hepatic stellate cells (HSCs) and liver tissues of CCl4-induced liver fibrosis." (PMID 33672311, 2021). "Consistent with our previous findings, BBR’s beneficial effects are linked with the downregulation of microRNA34a and long noncoding RNA H19, which are two important players in promoting NASH progression and liver fibrosis." (PMID 33494295, 2021). "In fibrotic liver tissues, USP4 was released through overexpression of lncRNA H19 sponging miR-148a and stabilized TβRI expression through deubiquitination to activate TGF-β signaling pathway which induced liver fibrosis." (PMID 32669974, 2020). "Thus, targeting of RNA H19 may represent a novel therapeutic approach for the hepatic fibrosis." (PMID 33409282, 2020). "Moreover, exosomal H19 accumulated in hepatic stellate cells (HSCs) and induced HSC activation, leading to liver fibrosis in bile duct ligation models." (PMID 37398637, 2023). "Interestingly, lncRNA H19 was significantly increased in hepatocytes in nonalcoholic steatohepatitis (NASH), cholestatic, and carbon tetrachloride (CCl4)‐induced liver fibrosis." (PMID 37398637, 2023). "Meanwhile, it has been shown that lncRNA H19 was increased in serum EVs from patients with biliary atresia and fibrosis and restrained the bioavailability of miRNA let-7 family to promote bile ducts proliferation and BDL-induced liver fibrosis." (PMID 36276639, 2022). "Increased hepatic/serum conjugated primary bile acids may be an important factor in cholestatic liver injury and liver fibrosis by activating S1PR2 and H19." (PMID 36224648, 2022). "In addition, exosomal lncRNA H19 also directly promoted HSC proliferation by enhancing G1/S cell cycle transition, leading to the exacerbation of liver fibrosis." (PMID 36276639, 2022). "H19 knockdown experiments also resulted in significant inhibition of HSC activation and attenuated liver fibrosis, suggesting that lncRNAH19 may be a potential target for antifibrotic therapeutic approaches." (PMID 34899344, 2021). "Furthermore, we found that overexpressed lncRNA H19 suppressed the level of small heterodimer partner (SHP) in hepatocytes by inhibiting its promoter activity and mRNA stability, thereby disrupting bile acid metabolism and resulting in liver fibrosis." (PMID 36276639, 2022). "In addition, after entered HUVECs, exogenous H19 exosomes activated the production and secretion of VEGF and thus increased tubular-like structures in the liver sinusoids, leading to the pathological neovascular response and liver fibrosis." (PMID 36276639, 2022). "Moreover, H19 could enhance TGF-β signaling in both hepatic stellate cells and hepatocytes and facilitate liver fibrosis." (PMID 33138822, 2020).
liver fibrosis (continued). "Previous investigations demonstrated that overexpression of lncRNAs such as H19, maternally expressed gene 3 (MEG3), growth arrest-specific transcript 5 (GAS5), Gm5091, NR_002155.1, and HIF 1alpha-antisense RNA 1 (HIF1A-AS1) can inhibit the progression of liver fibrosis." (PMID 32098245, 2020). "Therefore, both lncRNA H19 and USP4 can be used as targets to liver fibrosis treatment which may be the precancerous lesions of liver cancer." (PMID 32669974, 2020). "However, the dysexpression of miR-483 in liver fibrosis and HCC might result from other mechanism, such as H19 gene and its intragenic miRNA miR-675." (PMID 24801603, 2014).
pancreatic cancer (50 papers, 2010 to 2026). "In pancreatic cancer, not only H19 is overexpressed in tumor tissue and cell lines, but it is also positively associated with the ability of tumor invasion and migration." (PMID 38559560, 2024). "Hisashi Yoshimura revealed that H19 has important roles in pancreatic cancer metastasis, and that inhibition of H19 represents a novel candidate for pancreatic cancer therapy." (PMID 35330729, 2022). "It was found that H19 promoted pancreatic cancer cell invasion and migration by upregulation of HMGA2-mediated EMT through antagonizing let-7, demonstrating the critical role of H19/let-7/HMGA2/EMT signaling axis in pancreatic cancer progression." (PMID 34439315, 2021). "Knockdown of H19 in pancreatic cancer cells inhibited cell proliferation and tumor growth with G0/G1 arrest and downregulation of E2F-1 transcription factor." (PMID 34439315, 2021). "Our data are consistent with the notion that a reduced expression of H19 inhibited pancreatic cancer metastasis, which involved the H19-mediated regulation of the micro RNAs miR-194 and let-7." (PMID 33669381, 2021). "In pancreatic cancer, the expression of H19 was significantly increased and the overexpression of H19 was correlated with histological grade and invasion of pancreatic cancer." (PMID 34439315, 2021). "Recently, it was reported that H19 promoted pancreatic cancer cell invasion and metastasis via increasing cell adhesion and cancer stem cell self-renewal by regulating CD24 and integrin expression." (PMID 34421359, 2021). "A recent study revealed that H19 expression was increased in pancreatic cancer compared with normal pancreatic tissue." (PMID 34421359, 2021). "Another study showed that knocking-down H19 impaired the viability and growth of pancreatic cancer cells by decreasing E2F1 expression." (PMID 34421359, 2021). "In pancreatic cancer, H19 was reported to bind and inhibit miR‐194 to relieve the inhibition of PFTK1, thus activating Wnt signal transduction and increasing the proliferation and migration of tumor cells." (PMID 34598322, 2021). "Our results are consistent with previous work indicating that H19 expression is upregulated in several tumor entities, including pancreatic cancer." (PMID 33669381, 2021). "Abnormal expression of H19 and its downstream factors has been observed in pancreatic cancer by regulating the Wnt/β-catenin signaling pathway." (PMID 34977037, 2021). "For instance, BC-819, which is a DNA plasmid that drives the expression of the diphtheria toxin gene under the regulation of the H19 promoter, has been tested in several trials as a treatment for cancers overexpressing H19, including pancreatic cancer." (PMID 33628198, 2020). "LncRNA H19 is capable of increasing the metastasis of pancreatic cancer tissues through highly expressing pancreatic cancer tissues." (PMID 32337223, 2020). "Our findings suggest that H19 represents a novel therapeutic target for the metastasis of pancreatic cancer." (PMID 30410672, 2018). "This is exemplified by studies targeting regulatory elements in the H19 gene as an approach for pancreatic cancer therapy." (PMID 30238005, 2018). "We previously reported that in pancreatic cancer, inhibition of H19 reduced cancer metastasis in vivo, which demonstrated that H19 promotes the metastasis of PDAC cells." (PMID 30410672, 2018). "H19 is abnormally expressed in many types of cancers, including gastric, liver, colorectal, bladder, and pancreatic cancer, and increases the tumorigenic properties of tumor cells." (PMID 30071841, 2018). "H19 can promote pancreatic cancer metastasis by derepressing let-7’s suppression on its target HMGA2-mediated EMT." (PMID 28511643, 2017). "Next-generation sequencing suggests that H19 and miR-675 are down-regulated in neoplastic tissue compared to adjacent tissues in pancreatic cancer." (PMID 28212565, 2017).
pancreatic cancer (continued). "H19 expression was overexpressed in PDAC cells compared to adjacent normal cells with a higher levels of up-regulation in primary pancreatic tumors which subsequently metastasized, compared to those that did not metastasize." (PMID 26623562, 2016). "It suggested that H19 promoted pancreatic cancer metastasis by depressing let-7's suppression on its target HMGA2-mediated EMT." (PMID 27825121, 2016). "Five well-documented lncRNAs: H19, HOTAIR, HOTTIP, MALAT1, PVT1, which are most closely associated with pancreatic cancer from previous studies were selected as putative lncRNA biomarkers." (PMID 27028998, 2016). "Other studies indicate that H19 RNA is among the most increased RNAs in the PANC pancreatic cancer cell line that forms lung metastasis as compared to the parental cells." (PMID 26623562, 2016). "H19 also promoted pancreatic cancer cell invasion and migration at least partially by derepressing let-7's inhibition on its target gene HMGA2 which induces EMT." (PMID 27613832, 2016). "H19 promotes pancreatic cancer metastasis by releasing let-7-mediated inhibition on the target HMGA2-mediated EMT." (PMID 27391349, 2016). "We have also shown that in a pancreatic cancer cell line E-cadherin is totally ablated upon H19 expression as long as H19’s miR-675 seed region is intact." (PMID 26536864, 2015). "We found that 85% of human pancreatic tumors analyzed by in situ hybridization analyses showed moderated to strong expression of the H19 gene." (PMID 22701803, 2012). "An expression of H19 gene in 85% of the analyzed human pancreatic cancer samples determined by in situ hybridization analysis allowed us to suggest effectiveness of the BC-819 construct in this disease." (PMID 22701803, 2012). "Animals presenting pancreatic tumors were then treated with either DTA-H19 plasmid or the control plasmid (Luc-H19) administrated twice by direct injection into the tumor." (PMID 21052499, 2010). "The present work tested the feasibility of using the regulatory sequences of the H19 gene to express the diphtheria toxin A subunit for a DNA-based treatment for pancreatic cancer." (PMID 21052499, 2010). "We tested the expression of H19 gene in patients, and found that 65% of human pancreatic tumors analyzed showed moderated to strong expression of the gene." (PMID 21052499, 2010). "The activity of the H19 promoter was demonstrated in the human and hamster pancreatic tumor cells tested, leading to DTA expression." (PMID 21052499, 2010). "Following H19 expression confirmation, histological studies were performed in order to determine if the tumors were compatible with pancreatic carcinoma." (PMID 21052499, 2010). "The relevance of this orthotopic pancreatic carcinoma animal model was tested by studying the expression of the H19 gene which is a prerequisite to evaluate the therapeutic potential of the toxin expression vector in this animal model." (PMID 21052499, 2010). "Usually, H19 co-regulates with PFTAIRE protein kinase 1 (PFTK1) in pancreatic cancer." (PMID 38559560, 2024). "LncRNA H19 is significantly upregulated in pancreatic cancer cell lines and facilitates pancreatic cancer metastasis and EMT by directly targeting miR-675-3p, which binds to SOCS5, a member of the SOCS protein family that negatively regulates JAK2/STAT3 signaling." (PMID 35819532, 2022). "Additionally, H19 upregulates PFTK1 expression through targeting miR-194 in pancreatic cancer cells." (PMID 36310592, 2022). "Knockdown of H19 also inhibited metastasis of pancreatic cancer." (PMID 34439315, 2021). "In summary, H19 played a vital role in the prognosis of pancreatic cancer." (PMID 34421359, 2021). "In situ hybridization rates of H19 also suggested it had an important role in pancreatic cancer metastasis, which implied that suppressing H19 could be a novel treatment for pancreatic cancer." (PMID 34421359, 2021). "Recently, H19 was determined to be a promising therapeutic target for pancreatic cancer." (PMID 34977037, 2021).